APLN (apelin)
Diseases named in the same sentence as APLN in open-access papers (continued):
Sharing a sentence is not in itself a finding about the gene and the disease.
Alzheimer disease (12 papers, 2019 to 2025). A progressive, neurodegenerative disease characterized by loss of function and death of nerve cells in several areas of the brain leading to loss of cognitive function such as memory and language. "Our previous study found apelin-13 improves cognitive function in Alzheimer’s disease (AD) rats by inhibiting neuroinflammation through upregulation of BDNF/TrkB signaling pathway." (PMID 40867632, 2025). "Overall, these behavioral findings provide important insights into the mechanisms underlying the cognitive-enhancing effects of Apelin-13 and underscore the therapeutic potential of targeting the Nrf2-HO1 pathway for the treatment of Alzheimer’s disease." (PMID 38790466, 2024). "Apelin-13 can reduce memory deficits in a mouse model of Alzheimer’s disease." (PMID 36421846, 2022). "Similarly, SNPs rs16972837 and rs659517, both from gene RYR3, and SNP rs607483, are involved in the same pathways 4371-Apelin Signaling Pathway, 4713-Circadian Entrainment and 5010-Alzheimer’s Disease." (PMID 35033007, 2022). "Therefore, apelin derivatives offer a viable therapeutic option for the treatment of these chronic progressive neurological conditions such as Parkinson’s disease, Huntington’s disease, Alzheimer’s disease, and ALS." (PMID 39684795, 2024). "Apelin (gene name: Apln), an endogenous ligand that binds the G protein-coupled receptor angiotensin-like receptor 1 (APJ), exhibits a therapeutic effect on central nervous system (CNS) disorders such as stroke, Alzheimer’s disease, and Moyamoya disease." (PMID 35725619, 2022).
Cirrhosis (12 papers, 2011 to 2025). A chronic disorder of the liver in which liver tissue becomes scarred and is partially replaced by regenerative nodules and fibrotic tissue resulting in loss of liver function. "Compared to normal livers, APLN protein and gene expression are overexpressed in cirrhotic livers, increasing with the progression of cirrhosis." (PMID 39744169, 2025). "In the present study, the circulating level of apelin was significantly increased in rats with induced cirrhosis compared with healthy rats (p < 0.001)." (PMID 35831335, 2022). "With exception for At-ar-D1, all tested doses of all extracts significantly decreased serum apelin compared to rats with untreated induced cirrhosis." (PMID 35831335, 2022). "Previous studies have shown that apelin is overexpressed in HSCs from cirrhotic rats, and that the serum level of apelin is higher in patients or rats with cirrhosis than that in normal individuals." (PMID 31687083, 2019). "The expression of apelin is also enhanced under hypoxic or proinflammatory conditions in human hepatic stellate cells (HSCs), and it promotes liver fibrosis or cirrhosis progression." (PMID 31687083, 2019). "The circulating level of apelin was increased in patients with cirrhosis compared with healthy subjects." (PMID 29340118, 2017). "In rats with cirrhosis, the apelin levels were higher than controls, and apelin as well as APJ mRNA also showed an obvious rise in hepatic tissue." (PMID 29340118, 2017). "This is in line with previous investigations demonstrating that patients with cirrhosis showed significant increase in apelin circulating levels." (PMID 22007137, 2011). "However, both peptides, like apelin, are significantly reduced in patients with cirrhosis (BMP9, 218.1±9.5 vs 124.9±15.7 pg/ml, p<0.002; pBMP10, 3479.6 ± 298.3 vs 1236.1 ± 184.6 pg/ml, p < 0.0001)." (PMID 33171278, 2021). "The study demonstrated that AngII and ET-1 might exert some of their profibrotic effects in cirrhosis by activating the apelin signaling pathway." (PMID 31270645, 2019). "Furthermore, the level of circulating apelin was markedly increased in rats with cirrhosis than that in the controls." (PMID 31270645, 2019). "Apelin was weakly expressed in hepatic sinusoidal endothelial cells and in proliferated arterial capillaries directly connecting to the sinusoids in early stage cirrhotic liver, while apelin was strongly expressed in proliferated arterial capillaries in end stage cirrhosis." (PMID 29340118, 2017). "Apelin is one of two endogenous ligands for the G-protein-coupled apelin receptor expressed in the central nervous system and peripheral tissues, including the liver, and it is significantly reduced in the plasma of patients with early- (fibrosis) and late-stage (cirrhosis) liver disease." (PMID 40869103, 2025). "Moreover, apelin in human hepatic stellate cells enables the progression of fibrosis in cirrhosis." (PMID 35206438, 2022). "We hypothesised that apelin levels would also be downregulated in cirrhosis." (PMID 33171278, 2021). "It is unclear whether lowered levels of apelin are beneficial or detrimental in cirrhosis." (PMID 33171278, 2021). "In addition, circulating levels of apelin markedly increase in human and rats with cirrhosis." (PMID 31687083, 2019). "Furthermore, the circulating levels of apelin are markedly increased in rats with cirrhosis." (PMID 31687083, 2019). "Some studies also confirmed that the expression of apelin and APJ was low in the liver tissues of normal rats or human as compared to that in the case of cirrhosis." (PMID 31270645, 2019). "Our hypothesis was that changes in plasma apelin levels would positively correlate with the known reduction of BMP9 and BMP10 in cirrhosis." (PMID 33171278, 2021). "The apelin/APJ was activated in patients with cirrhosis and blocking apelin/APJ system could alleviate symptoms of hepatic cirrhosis, suggesting that apelin/APJ system is a potential therapeutic target of hepatic cirrhosis." (PMID 29340118, 2017).
Cirrhosis (continued). "The emerging role of apelin in CLD is complex, as described in a recent report linking apelin to the initiation and maintenance of the inflammatory and fibrogenic processes occurring in the fibrotic liver, as well as to the vascular and haemodynamic abnormalities in cirrhosis and its complications." (PMID 22007137, 2011). "Furthermore, pathway analysis suggested enrichment of estrogen and apelin signaling pathways in PoPH as compared to the non-PoPH cirrhosis liver, and biomarker analyses confirmed low levels of circulating BMP9 distinguished PoPH from non-PoPH cirrhosis and IPAH." (PMID 37558836, 2023).
melanoma (12 papers, 2014 to 2025). A malignant, usually aggressive tumor composed of atypical, neoplastic melanocytes. "Murine B16 and human A375 melanoma cell lines were stably transfected with apelin encoding or control vectors." (PMID 33707612, 2021). "We also analyzed publicly available databases to explore associations between apelin gene expression and clinical outcome in patients with melanoma." (PMID 33707612, 2021). "As further proof-of-principle, MM54 attenuates the pro-tumourigenic effects of apelin in a mouse melanoma lung metastasis model, suggesting that apelin receptor blocking therapy is not necessarily limited to brain cancers." (PMID 38803685, 2024). "Correlating with this expression, expression of the mesenchymal maker, Zeb1, was also higher in APJ-KO melanoma and B16/apelin cells than in B16/WT cells." (PMID 36776217, 2023). "In APJ-KO mice, Apelin overexpression in B16/BL6 (B16) melanoma cells induced greater tumor growth than controls." (PMID 36776217, 2023). "An excess amount of apelin induced the growth of B16 melanoma cells by affecting APJ in tumor cells." (PMID 36776217, 2023). "Having demonstrated that apelin promotes metastatic growth in preclinical models of murine and human melanoma, we next investigated the clinical relevance of this observation." (PMID 33707612, 2021). "Studying the circulating apelin levels, we found that the plasma levels of apelin were significantly elevated in patients with melanoma (vs. healthy controls, 1.4590 ± 0.2676 ng/ml vs. 0.7704 ± 0.7117 ng/ml, respectively, p = 0.0011)." (PMID 33707612, 2021). "Next, research revealed that, also, apelin overexpression increased the number and size of melanoma lung metastases in mice." (PMID 34068679, 2021). "In order to investigate the effect of apelin overexpression on lung metastases in a mouse model of melanoma, apelin-overexpressing and control B16 cells were injected intravenously into C57Bl/6 mice." (PMID 33707612, 2021). "In our study, MM54, a competitive APJ antagonist, inhibited tumor (lymph)angiogenesis and tumor cell proliferation and thus attenuated apelin-induced growth of melanoma lung metastasis." (PMID 33707612, 2021). "The overexpression of apelin in melanoma cells was validated by reverse transcription-quantitative polymerase chain reaction (RT-qPCR)." (PMID 33707612, 2021). "Mice injected with apelin-overexpressing melanoma cells were also treated with the APJ antagonist MM54 or saline, twice a week, intraperitoneally." (PMID 33707612, 2021). "Melanoma cell proliferation rates and lymph and blood microvessel densities were significantly higher in the apelin-overexpressing pulmonary metastases." (PMID 33707612, 2021). "In our in vivo experiments, apelin significantly increased the number and size of lung metastases of murine melanoma cells." (PMID 33707612, 2021). "Apelin was also shown to modulate the invasiveness of melanoma cells and to induce its metastasis to lymph nodes." (PMID 30127323, 2018). "More importantly, apelin overexpression of murine B16 melanoma cells significantly increased the burden and intratumoral lymphangiogenesis of tumors growing subcutaneously in mice." (PMID 24962866, 2014). "Our studies to address this goal involved experiments with B16 mouse melanoma cells stably transfected with murine apelin (B16-apelin) or with an empty plasmid vector (B16-mock)." (PMID 24962866, 2014). "We found that overexpression of apelin in B16 melanoma cells induced the growth of tumors." (PMID 36776217, 2023). "Circulating levels of apelin were measured in 40 blood samples of melanoma patients." (PMID 33707612, 2021). "Moreover, apelin overexpression in mouse melanoma cells promoted in vivo tumor growth and increased intratumoral lymphangiogenesis and lymph node metastasis." (PMID 33707612, 2021). "Consequently, in this study we focus on the role of the (lymph)angiogenic apelin molecule in pulmonary metastases of malignant melanoma." (PMID 33707612, 2021).
melanoma (continued). "Moreover, when the single melanoma cells were let to form spheroids in a collagen gel, tumor cells more visibly spread out from the spheroids in case of apelin overexpressing melanoma cells compared to the cells transfected with control vector." (PMID 33707612, 2021). "Furthermore, in order to study the clinical relevance of expression level of apelin gene in patients with melanoma, we performed comparative statistical analyses using several publicly available datasets." (PMID 33707612, 2021). "In mice, apelin-13 could stimulate lymph nodes metastasis of implanted apelin-overexpressing melanoma cells." (PMID 29875677, 2018). "Furthermore, implantation of melanoma cells overexpressing apelin into mice resulted in an increase of intratumor lymphangiogenesis and metastasis to lymph nodes." (PMID 29875677, 2018). "In addition, apelin-13 can induce lymph node metastasis in mice transplanted with APLN-overexpressing melanoma cells 58 and high levels of APLN expression in bladder tumor tissue are associated with a higher tumor stage and a higher probability of distant metastasis, as well as vascular invasion." (PMID 36632453, 2023). "The apelin antagonist MM54 has been shown to be effective in a mouse models of GBM and a mouse melanoma lung metastasis model." (PMID 38803685, 2024). "As a first step, we performed sulforhodamine B (SRB) assay with the control and apelin-overexpressing B16 and A375 cells and found that apelin had no impact on the proliferation of melanoma cell lines in two-dimensional cell cultures." (PMID 33707612, 2021). "Additionally, we detected significantly elevated circulating apelin and VEGF levels in patients with melanoma compared to healthy controls." (PMID 33707612, 2021). "Apelin overexpression significantly increased melanoma cell migration and invasion in vitro, but it had no impact on its proliferation." (PMID 33707612, 2021). "Interestingly, apelin and VEGF plasma concentrations were more elevated in patients with melanoma than in healthy individuals." (PMID 34068679, 2021). "Adipocytes in obese patients with melanoma release high amounts of pro-inflammatory cytokines and growth factors (IL-6, IL-32 or TNF-α) and molecules involved in the angiogenesis enhancement (OPN—osteopontin, chemerin, apelin and PAI-1) that modulate melanoma proliferation." (PMID 40136652, 2025). "Additionally, in vitro studies showed that higher apelin expression enhances the migratory and invasive abilities of melanoma cell lines, but does not influence their proliferation." (PMID 34068679, 2021). "Indeed, miR-4286 inhibition resulted in degradation of folylpolyglutamate synthase, RNA polymerase I-specific transcription initiation factor, apelin, G-protein-coupled receptor 55, and high-mobility group A1 protein mRNA in BRO melanoma cells, as measured by real-time PCR." (PMID 28005927, 2016).
renal fibrosis (12 papers, 2018 to 2024). A final common manifestation of a wide variety of chronic kidney diseases characterized by glomerulosclerosis and tubulointerstitial fibrosis. "This study helps to clarify the upstream and downstream regulatory mechanisms of Apelin in renal fibrosis associated with DN, providing a theoretical basis for Apelin as an endogenous anti-fibrotic therapeutic target for DN." (PMID 39014438, 2024). "Additionally, we also observed that the expression of α-SMA, CTGF, and cdh1, which are involved in the apelin signaling pathway, was associated with renal fibrosis, leading us to speculate that this pathway may play an important role in the process of pulmonary fibrosis." (PMID 33176882, 2020). "The only clear effect obtained after apelin supplementation was a reduction of renal fibrosis in mice of advanced age (24 weeks) after apelin treatment as estimated by Sirius red staining." (PMID 31337837, 2019). "It was observed that apelin could attenuate renal fibrosis by suppressing the EMT of podocytes and tubules through TGFβ/Smad signaling." (PMID 36785790, 2023). "Moreover, accumulating evidence suggests that apelin displays an anti-fibrotic effect in the skin 24, cardiac 25, cardiovascular 26, and renal fibrosis 27, 28, which affects the TGF-β signaling." (PMID 37705751, 2023). "On the contrary, apelin is beneficial for renal fibrosis and pulmonary fibrosis." (PMID 32207519, 2020). "A previous study reported that the apelin-APJ axis inhibits fibrosis in several organs and has a synergistic effect on attenuating renal fibrosis." (PMID 34465345, 2021). "Numerous evidences indicate that apelin and APLNR play a key role in various kidney diseases, such as renal fibrosis, renal ischemia/reperfusion injury, polycystic kidney disease, and diabetic nephropathy." (PMID 33436040, 2021). "Previous studies indicated that Apelin, an adipokine which is upregulated in DKD, was negatively correlated to renal fibrosis and TGFβ in polycystic kidney disease." (PMID 30301930, 2018). "Apelin-13 could suppress the transforming growth factor-β1 (TGF-β1) expression, which belongs to a critical mediator of renal fibrosis, thus alleviate kidney tissue fibrosis." (PMID 39014438, 2024). "Moreover, apelin-13 positively influenced the expression of fibrosis-related proteins such as E-cadherin and α-SMA, suggesting a role in mitigating renal fibrosis." (PMID 39857634, 2024). "Particularly, apelin and APLNR could inhibit the deposition of extracellular matrix (ECM) and attenuate renal fibrosis by acting on TGF-β." (PMID 33436040, 2021). "Conversely, elevated apelin levels have been associated with adverse outcomes, including increased markers of renal fibrosis and dysfunction, such as TGF-β1 and urinary protein levels, indicating that high apelin levels may signal worsening kidney function or serve as biomarkers for advanced DKD." (PMID 39857634, 2024). "Increased nitric oxide production through the apelin/APJ/protein kinase B (Akt)/endothelial nitric oxide synthase (eNOS) pathway may, at least in part, contribute to the alleviating effect of losartan in unilateral ureteral obstruction-induced renal fibrosis in mice." (PMID 32207519, 2020). "Apelin inhibits the expression of TGF-β/smad, and TGF-β/smad may regulate RUNX3 to enter the nucleus, thereby implementing the negative feedback regulation of Apelin against renal fibrosis." (PMID 39014438, 2024).